CDCA4 (cell division cycle associated 4)
Description:
May participate in the regulation of cell proliferation through the E2F/RB pathway. May be involved in molecular regulation of hematopoietic stem cells and progenitor cell lineage commitment and differentiation (By similarity).
Synonyms: HEPP; SEI-3; TRIP-Br3; FLJ20764; SEI-3/HEPP
Tractability: Antibody: its Gene Ontology location is reachable by antibodies, with high confidence. PROTAC: ubiquitination databases record sites on it.
Gene: Protein-coding gene on chromosome 14 (105,008,533 to 105,025,018, reverse strand). Ensembl gene ENSG00000170779.
Subcellular location: Nucleus
Subcellular location (Human Protein Atlas): Nucleoplasm; Cytosol; Plasma membrane
Gene Ontology:
Molecular function: protein binding; transcription coactivator activity
Biological process: positive regulation of DNA-templated transcription
Cellular component: nucleoplasm; cytoplasm; nucleus
Genetic constraint (gnomAD): Loss-of-function variants: 0 observed, 0.65 expected, observed/expected ratio (o/e) 0, 90% interval 0 to 1.81. That is too few expected variants to judge how well the gene tolerates losing a copy. Missense variants: 294 observed, 337.24 expected, observed/expected ratio (o/e) 0.87, 90% interval 0.79 to 0.96. Synonymous variants: 130 observed, 143.21 expected, observed/expected ratio (o/e) 0.91, 90% interval 0.79 to 1.05.
Homologues: Orthologues: chimpanzee CDCA4 (99% identical), macaque CDCA4 (97% identical), guinea pig CDCA4 (75% identical), dog CDCA4 (73% identical), mouse Cdca4 (73% identical), rat Cdca4 (72% identical), pig CDCA4 (58% identical), tropical clawed frog cdca4 (57% identical), zebrafish cdca4 (49% identical), Drosophila melanogaster tara (22% identical). Paralogues in human: SERTAD2 (30% identical).
Diseases named in the same sentence as CDCA4 in open-access papers:
CDCA4 is named in the same sentence as 39 diseases in open-access papers, as found by Europe PMC text mining. Sharing a sentence is not in itself a finding about the gene and the disease. The quoted sentences say what the papers report.
breast cancer (12 papers, 2018 to 2025). A primary or metastatic malignant neoplasm involving the breast. "CDCA4 is upregulated in non-small cell lung cancer, breast cancer, osteosarcoma, and ovarian cancer, making it a potential biomarker and key mediator in various malignancies." (PMID 40565588, 2025). "In breast cancer, non-small cell lung cancer, osteosarcoma, and squamous cell carcinoma of the head and neck, CDCA4 has been found to be up-regulated." (PMID 38098487, 2023). "CDCA4 was shown to be upregulated in breast cancer, non-small cell lung cancer, osteosarcoma, head and neck squamous cell carcinoma, and ovarian cancer." (PMID 35251007, 2022). "CDCA4 differential expression was also shown to be greater in a number of human malignancies, including breast cancer, non-small cell lung cancer, osteosarcoma, HNSC, and ovarian cancer." (PMID 35251007, 2022). "The apoptotic rate of the cells significantly increased suggesting that CDCA4 increased the proliferation of cancer cells in MCF-7/ADM human breast cancer cells." (PMID 35126099, 2021). "The cell division cycle-dissociated protein 4 (CDCA4) knock-down by RNA interference in MCF-7 human breast cancer cell lines resistant to Adriamycin (MCF-7/ADM) decreased the percentage of cancer cells by 50%." (PMID 35126099, 2021). "Basal subtype had the highest expression of CDCA4, while the lowest was in the luminal-like subtype of breast cancer." (PMID 29467944, 2018). "In breast cancer, transfecting with CDCA4 in vitro could enhance the proliferation and reduce the apoptosis of MCF-7/ADM cells." (PMID 34824999, 2021). "Although previous studies have demonstrated that CDCA4 could promote cell proliferation in human breast cancer and maligant melanoma, its other potential influence on tumor progression is still unclear." (PMID 33436008, 2021). "From the CCLE analysis, CDCA4 expression levels in breast cancer cell lines were high." (PMID 29467944, 2018). "CDCA4 is aberrantly regulated in various cancers, comprising triple-negative breast cancer (BC), Wilm’s tumour, melanoma, and osteosarcoma, and is associated with poor patient outcomes." (PMID 36185189, 2022). "In breast cancer CDCA4 could enhance cancer cell proliferation and reduce apoptosis." (PMID 33436008, 2021). "CDCA4 has been shown to influence cell proliferation and death in the MCF7/ADM human breast cancer cell line via downregulating genes in the Nrf2 signaling pathway." (PMID 35251007, 2022). "There is evidence that overexpression of CDCA4 stimulates proliferation and inhibits apoptosis in MCF-7/ADM human breast cancer cells." (PMID 36185189, 2022). "The CDCA4 mRNA expression level in breast cancer subtypes was not as high as that of the CDCA3 level." (PMID 29467944, 2018).
melanoma (7 papers, 2021 to 2024). A malignant, usually aggressive tumor composed of atypical, neoplastic melanocytes. "In vitro studies on breast, cervical and malignant melanoma have investigated the expression and function of CDCA4 in tumorigenesis." (PMID 36185189, 2022). "Down-regulation of CDCA4, a miR-15a target, leads to cell cycle arrest in malignant melanoma cells in the G0/G1 phase." (PMID 36185189, 2022). "In melanoma, miR-15a and miR-29c-3p are regulators of CDCA4, which is involved in controlling cell proliferation, invasion, and apoptosis." (PMID 35269844, 2022). "Cell division cycle-associated protein 4 (CDCA4) has been reported to interact with miRNA-15a and contribute to cells growth and invasion of malignant melanoma in vitro." (PMID 34090440, 2021). "When the predictive power of all of these genes was tested on an ICI-treated melanoma patient cohort, 11 out of the 13 in vitro stable (containing IRGs SOX4, DEK, and HSPA1B) and AQP1 and CDCA4 in vivo stable DEGs were differentially expressed in the tumors of ICI responder melanoma patients." (PMID 35269844, 2022).
osteosarcoma (7 papers, 2021 to 2025). A usually aggressive malignant bone-forming mesenchymal neoplasm, predominantly affecting adolescents and young adults. "Our results indicated that CDCA4 was increased in osteosarcoma tissues and cell lines, and its level had association with high mortality of osteosarcoma patients." (PMID 33613651, 2021). "Our data collectively suggested that aerobic exercise-related CDCA4 displayed as a potential carcinogene in osteosarcoma development, implying that it was a prospective marker for osteosarcoma prognosis." (PMID 33613651, 2021). "We conducted lots of functional experiments to uncover CDCA4 function and its corresponding mechanism in osteosarcoma." (PMID 33613651, 2021). "For clearly clarifying CDCA4 function in osteosarcoma occurrence and development, we transfected siRNA specifically targeting CDCA4 into SW1353 and U2OS cells, respectively." (PMID 33613651, 2021). "In vitro functional test data showed that CDCA4 was closely related to the regulation of osteosarcoma cell proliferation, migration and invasion." (PMID 33613651, 2021). "We conducted a series of experiments in the study to explore the exact role of CDCA4 in osteosarcoma progression." (PMID 33613651, 2021). "The results of Transwell assay showed that knocking out CDCA4 inhibited the invasion and migration of osteosarcoma cells." (PMID 33613651, 2021). "Kaplan-Meier survival analysis revealed that highly expressed CDCA4 in osteosarcoma patients led to shorter overall survival (OS) and disease free survival time." (PMID 33613651, 2021). "Subsequently, qRT-PCR analysis showed that CDCA4 was highly expression in osteosarcoma tissues and cell lines." (PMID 33613651, 2021). "Next, we kept on evaluating CDCA4 expression in osteosarcoma cells (HOS, SW1353, and U2OS) and normal cell (hFOB1.19)." (PMID 33613651, 2021). "Quantitative reverse transcription polymerase chain reaction (qRT-PCR) and tumor genome atlas (TCGA) data mining were applied to measure aerobic exercise-related gene CDCA4 level in osteosarcoma tissue." (PMID 33613651, 2021). "In order to explore the role of CDCA4 in osteosarcoma, based on the TCGA database, CDCA4 expression, prognostic value and clinicopathological features in osteosarcoma were analyzed." (PMID 33613651, 2021). "To investigate CDCA4 functions in osteosarcoma, we measured CDCA4 expression in 12 paired normal and osteosarcoma tissues by qRT-PCR assays." (PMID 33613651, 2021). "Our data showed that CDCA4 was elevated in osteosarcoma tissues and cell lines and affected cell proliferation, migration, and invasion." (PMID 33613651, 2021). "The data indicated compared to normal tissue, CDCA4 expression level was largely raised in osteosarcoma tissues." (PMID 33613651, 2021). "In osteosarcoma, the miR-503–5p/CDCA4 axis regulates the genesis and development of cancer cells." (PMID 40644833, 2025). "Functional assays demonstrated that osteosarcoma cancer cell proliferation, invasion, and migration could be dramatically inhibited upon knockdown CDCA4." (PMID 33613651, 2021). "In order to explore whether CDCA4 expression was related to the clinicopathological features of osteosarcoma, we further analyzed the clinical data of osteosarcoma patients." (PMID 33613651, 2021). "All in all, these data suggested that aerobic exercise could affect osteosarcoma by regulating CDCA4 expression which provided a whole new perspective for the study of osteosarcoma." (PMID 33613651, 2021). "Our data indicated that osteosarcoma tissues and cell lines highly expressed CDCA4." (PMID 33613651, 2021). "Taken together, our data indicated that reduction of CDCA4 could result in inhibition of osteosarcoma cell proliferation, migration, and invasion." (PMID 33613651, 2021). "The results showed that CDCA4 expression was greatly enhanced in osteosarcoma cells." (PMID 33613651, 2021).
osteosarcoma (continued). "Our data suggested that CDCA4 could facilitate osteosarcoma development, and gave a hint that CDCA4 was a candidate target in the treatment of osteosarcoma, aerobic exercise might help the treatment and prognosis of patients with osteosarcoma." (PMID 33613651, 2021). "Therefore, in our study, we guess that aerobic exercise can decrease the expression of oncogene CDCA4 to impede cancer development, indicating that appropriate aerobic exercise might be helpful to the treatment and prognosis of patients with osteosarcoma." (PMID 33613651, 2021). "In summary, our findings indicate that CDCA4 may play a carcinogenic role in osteogenic sarcoma." (PMID 33613651, 2021). "Another study demonstrated that HMS sponges another miRNA, miR-503-5p to upregulate cell cycle gene CDCA4, establishing an oncogenic role of HMS in osteosarcoma." (PMID 34302808, 2021). "However, the molecular mechanism of CDCA4 in osteosarcoma has not been clarified." (PMID 33613651, 2021).
triple-negative breast carcinoma (6 papers, 2020 to 2022). An invasive breast carcinoma which is negative for expression of estrogen receptor (ER), progesterone receptor (PR), and human epidermal growth factor receptor 2 (HER2). "CDCA4 has been reported to significantly impact cell proliferation and apoptosis in human triple negative breast cancer." (PMID 34090440, 2021). "For example, reducing CDCA4 expression can inhibit the proliferation of MDA-MB-231 cells in triple negative breast cancer." (PMID 34772428, 2021). "Moreover, CDCA4 is involved in the triple-negative breast cancer (TNBC) cells, and it is shown that RNA interference of CDCA4 markedly increases cell apoptotic rate." (PMID 32104702, 2020). "A recent study also suggested that CDCA4 may be involved in regulating triple negative breast cancer (TNBC) progression." (PMID 32716971, 2020).
non-small cell lung carcinoma (5 papers, 2021 to 2025). A group of at least three distinct histological types of lung cancer, including non-small cell squamous cell carcinoma, adenocarcinoma, and large cell carcinoma. "In the KEGG category, CDCA4 is significantly enriched in non-small cell lung cancer." (PMID 38701314, 2024). "The function of CDCA4 in Non-small cell lung cancer (NSCLC) was unknown." (PMID 33436008, 2021).
ovarian carcinoma (5 papers, 2013 to 2025). A malignant neoplasm originating from the surface ovarian epithelium. "Notably, overexpression of CDCA4 is directly associated with reduced post-progression survival (PPS) in ovarian cancer." (PMID 36185189, 2022). "Furthermore, ovarian cancer patients with elevated CDCA4 expression levels were related to the lower post-progression survival." (PMID 36185189, 2022). "Moreover, miR-744-5p was reported to facilitate cell apoptosis by targeting HNRNPC and NFIX in ovarian cancer.In this study, CDCA4 was identified as the target gene of miR-744-5p and was negatively regulated by miR-744-5p." (PMID 34090440, 2021). "Further studies are necessary to determine whether miR-503 induces cancer cell growth or migration/invasion, and whether CDCA4 is a direct target gene of miR-503, as well as to define the oncogenic function of miR-503 in this subset of ovarian cancers." (PMID 23522567, 2013).
hepatocellular carcinoma (3 papers, 2020 to 2024). A malignant tumor that arises from hepatocytes. "This further supports the association of CDCA4 with the immune microenvironment in hepatocellular carcinoma and provides more insight into its potential role in immune regulation." (PMID 38701314, 2024). "In conclusion, our study demonstrated that high CDCA4 expression was closely associated with immune infiltration and poor prognosis in hepatocellular carcinoma." (PMID 38701314, 2024). "This indicates that the expression level of CDCA4 can affect patients with hepatocellular carcinoma, which has further research value." (PMID 38701314, 2024). "This suggests that CDCA4 has potential prognostic value in hepatocellular carcinoma and may be evaluated as an important prognostic indicator." (PMID 38701314, 2024). "In conclusion, our findings suggested that CDCA2, CDCA3, CDCA4, CDCA5, and CDCA8 might have potential diagnostic and prognostic values for hepatocellular carcinoma." (PMID 32913466, 2020). "Molecular biology experiments including Western blotting, flow cytometry, EDU staining, Transwell and Wound Healing assay to validate the cancer promoting role of CDCA4 in hepatocellular carcinoma (HCC)." (PMID 35251007, 2022). "Roessler's 19 two datasets indicated that CDCD3, CDCA4 and CDCA8 were overexpressed in hepatocellular carcinoma." (PMID 32913466, 2020). "In conclusion, we supposed that CDCA2, CDCA3, CDCA4, CDCA5 and CDCA8 might be oncogenes in hepatocellular carcinoma." (PMID 32913466, 2020). "In Wurmbach's dataset 20, CDCA2, CDCA3, CDCA4, CDCA5 and CDCA8 were up-regulated in hepatocellular carcinoma (HCC), with fold changes of 1.813, 3.214, 1.832, 2.422 and 1.693, respectively." (PMID 32913466, 2020).
lung adenocarcinoma (3 papers, 2021 to 2025). A carcinoma that arises from the lung and is characterized by the presence of malignant glandular epithelial cells. "Increased CDCA4 expression is positively correlated with increased T, N, and pathological stages and worse primary therapy outcomes in patients with lung adenocarcinoma." (PMID 39969065, 2025). "CDCA4 interacts with IGF2BP1 to regulate lung adenocarcinoma proliferation via the PI3K/AKT pathway." (PMID 39969065, 2025). "In addition, CDCA4 is related to immune infiltrates in lung adenocarcinoma." (PMID 36185189, 2022). "However, there is a little study to explore CDCA4 expression in lung adenocarcinoma." (PMID 36185189, 2022).
lung squamous cell carcinoma (3 papers, 2021 to 2024). "In lung squamous cell carcinoma (LUSC), CDCA4 overexpression significantly inhibited apoptosis, and enhanced the invasion and migration in vitro, leading to a deterioration of LUSC progression." (PMID 36185189, 2022).
liver cancer (2 papers, 2022 to 2024). An epithelial or non-epithelial malignant neoplasm that arises from the liver. "Through this investigation, we aim to elucidate the associations between CDCA4 and potential targets or signaling pathways pertinent to the onset and progression of liver cancer." (PMID 38701314, 2024). "High expression of CDCA4 is frequently linked to poor prognosis and advanced tumor stage in liver cancer." (PMID 38701314, 2024). "K-M plot was used to further analyze the correlation between CDCA4 expression and cancer prognosis, and the results of the correlation analysis indicated that CDCA4 expression was associated with the prognosis of various cancer types, including breast, ovarian, lung, gastric and liver cancer." (PMID 35251007, 2022). "In this context, CDCA4 is considered an independent prognostic factor in liver cancer, with patients exhibiting lower CDCA4 expression showing better prognosis compared to those with higher expression." (PMID 38701314, 2024). "Investigating the expression of CDCA4 and its prognostic value in liver cancer is the aim of this investigation, along with its influence on the immune microenvironment." (PMID 38701314, 2024). "In the future, the development of targeted or novel immunotherapies against CDCA4 may reduce the mortality rate of liver cancer patients." (PMID 38701314, 2024). "Thirdly, the specific mechanisms of CDCA4 in liver cancer remain unclear, and future experiments will be conducted to explore its functions and mechanisms in more depth." (PMID 38701314, 2024).
asthma (1 paper, 2024). "In terms of pathway enrichment (KEGG), the CDCA4-immune related genes were significantly enriched in Asthma." (PMID 38701314, 2024).
cervical cancer (1 paper, 2021). A primary or metastatic malignant neoplasm involving the cervix. "However, CDCA4 worked as a tumor suppressor gene in cervical cancer as the knockdown of CDCA4 could promote cell proliferation." (PMID 33436008, 2021).
Chagas disease (1 paper, 2022). A parasitic infection caused by Trypanosoma cruzi. "Dopaminergic Synapse, AMPK, Sphingolipid, Chagas Disease, mRNA Surveillance were significantly enriched pathways in positive and negative correlation genes with CDCA4." (PMID 35251007, 2022).
diffuse large B-cell lymphoma (1 paper, 2022). "In Diffuse Large B-cell Lymphoma (DLBC) and TGCT, CDCA4 expression was inversely connected with MSI, but it was positively correlated in COAD, KICH, MESO, SARC, Stomach adenocarcinoma (STAD) and UCEC." (PMID 35251007, 2022).
esophageal cancer (1 paper, 2023). A primary or metastatic malignant neoplasm involving the esophagus. "constructed a prognostic map for esophageal cancer, utilizing eight genes, including CDCA4, UBE2Z, AMTN, AK1, TLE1, FXN, ZBTB6, and APLN." (PMID 38098487, 2023).
glioma (1 paper, 2024). A benign or malignant brain and spinal cord tumor that arises from glial cells (astrocytes, oligodendrocytes, ependymal cells). "Combined with the GDSC drug database, CDCA2, CDCA4, CDCA5, CDCA7, and CDCA8 have potential as clinical drug treatments for glioma." (PMID 38181024, 2024). "CDCA2, CDCA4, CDCA5, CDCA7, and CDCA8 showed high accuracy for diagnosing gliomas, with CDCA7 having the highest accuracy (AUC: 0.982)." (PMID 38181024, 2024). "CDCA2, CDCA3, CDCA4, CDCA5, CDCA7, and CDCA8 were significantly highly expressed in glioma samples." (PMID 38181024, 2024).
head and neck squamous cell carcinoma (1 paper, 2022). A squamous cell carcinoma that arises from any of the following anatomic sites: lip and oral cavity, nasal cavity, paranasal sinuses, pharynx, larynx, and salivary glands. "In BLCA, Head and Neck squamous cell carcinoma (HNSC), LUSC, Ovarian serous cystadenocarcinoma (OV), and Sarcoma (SARC), there is a substantial positive connection between CDCA4 CNV and mRNA expression." (PMID 35251007, 2022).
lung carcinoma (1 paper, 2025). "However, miR-15a-5p, which is underexpressed in lung cancer tissues, negatively regulates the proliferation and migration of A549 lung cancer cells by targeting CDCA4." (PMID 40028322, 2025).